PXN (paxillin)
Diseases named in the same sentence as PXN in open-access papers (continued):
Sharing a sentence is not in itself a finding about the gene and the disease.
lung cancer (continued). "Paxillin is an oncogene that is involved in cell migration; it is highly expressed in lung cancer tissues, and positively correlates with increased EMT." (PMID 25337707, 2014). "As an oncogene involved in cell migration and in lung cancer tissues, paxillin was also highly expressed, amplifed, and correlated with increased EMT." (PMID 24023938, 2013). "Enhanced Ki-67 protein, a cellular marker for proliferation, increased the growth and proliferation of lung cancer cell H522 in vivo with overexpression of paxillin." (PMID 23209815, 2012). "The matrix adhesion structures of the lung cancer cells were investigated by immunofluorescence localization of a phosphospecific antibody to tyrosine-118 of paxillin." (PMID 16756685, 2006). "To investigate whether PXN is functionally correlated with CD155 overexpression in lung cancer, we examined the effects of PXN on cell phenotypes." (PMID 40634277, 2025). "Importantly, the level of CD155 was strong positively correlated with that of PXN (p < 0.0001, R = 0.554) in lung cancer." (PMID 40634277, 2025). "In addition, flow cytometric analysis elucidated that inhibiting the PXN pathway with the small-molecule inhibitor 6-B345TTQ enhanced the killing of lung cancer cells by CD8+ T cells." (PMID 39034411, 2024). "In lung cancer, integrin β4/PXN/FAK complex mediates cisplatin resistance through regulating ubiquitin specific peptidase 1 (USP1) and voltage-dependent anion channel 1 (VDAC1), which are associated with mitochondrial function and maintaining genomic stability." (PMID 37770930, 2023). "Also, phosphorylation of Rac1 and Cdc42, two downstream molecules in the FAK/Src/paxillin signaling pathway, is decreased in lung cancer cells after deguelin-based treatment." (PMID 36362132, 2022). "Moreover, two key proteins in focal adhesion complexes, PXN and integrin B4, directly bind to each other, and this complex enhanced cisplatin resistance in lung cancer cells." (PMID 33322675, 2020). "Another study showed that PXN phosphorylation may contribute to cisplatin resistance via the ERK-mediated activation of Bcl-2 transcription in lung cancer." (PMID 33322675, 2020). "Therefore, we propose DBL inhibits lung cancer cell line A549 metastasis through inhibition of the FAK/paxillin signaling pathway." (PMID 28350337, 2017). "Similarly, we found that EL reduced FAK Y397 phosphorylation and decreased phosphorylated paxillin in lung cancer cell lines." (PMID 28068967, 2017). "Moreover, a recent report indicated that paxillin upregulation in response to miR-218 reduction enhanced tumor growth and metastasis in lung cancer." (PMID 23209815, 2012). "Moreover, it enhances progression of non‐small cell lung cancer via regulation of PXN." (PMID 37154079, 2023). "It has been reported that phosphorylated paxillin increases Bcl-2 expression through the ERK signaling pathway as the cause of cisplatin resistance in non-small cell lung cancer, and Src or ERK inhibitors help restore the sensitivity of lung cancer patients to cisplatin chemotherapy." (PMID 37175948, 2023). "Importantly, Paxillin played a crucial role in the progression of lung cancer." (PMID 33162799, 2020). "A previous study reported that PXN could inhibit lung cancer proliferation and motility." (PMID 24180516, 2013). "Conversely, patients with lung cancer exhibiting lower CXCL5 expression displayed less CD66b+ neutrophil infiltration, greater CD8+ T cell infiltration, and lower levels of p-PXN, PD-L1, GM-CSF, PD-1, and TIM-3 expressions." (PMID 39034411, 2024). "In this study, we demonstrated that tumor-secreted CXCL5 induces phosphorylation of the PXN/AKT pathway, leading to PD-L1 upregulation in lung cancer and enabling the evasion of immune surveillance by CD8+ T cells." (PMID 39034411, 2024).
lung cancer (continued). "In a cohort comprising primary tumors from 208 patients with lung cancer, we measured the number of CD66b+ neutrophils and the expression of CXCL5, p-PXN, PD-L1, GM-CSF, CD8, PD-1, and T cell immunoglobulin-3 (TIM-3)." (PMID 39034411, 2024). "Chemoresistance, such as cisplatin resistance, is exaggerated when integrin β4 binds to paxillin (PXN) and FAK to form a focal adhesion complex in lung cancer." (PMID 37770930, 2023). "Previous studies support our finding that NTSR1-overexpression enhances lung cancer cell migration and invasion, increases FAK and paxillin phosphorylation, and affects F-actin distribution." (PMID 37726723, 2023). "The activity prediction algorithm was then implemented for the regulatory networks of six important lung cancer oncogenes (FAK, PXN, MET, RON (MST1R), EPHA2, AXL)." (PMID 29731983, 2018). "While serum elicited actin reorganization and assembly of paxillin in the focal adhesion plaque, treatment of ISL abolished these two serum-induced events in lung cancer cells, suggesting that ISL deters cell migration by impairing cytoskeleton reorganization." (PMID 30285892, 2018). "Paxillin and FAK activity are reduced in lung cancer cell lines following wiskostatin and nWASP knockdown as shown by immunofluorescence and western blot." (PMID 28351346, 2017). "Our findings also suggested that the inhibitory effects of AC-93253 iodide on lung cancer progression may be attributable to its ability to modulate multiple proteins, including Src, PI3K, JNK, Paxillin, p130cas, MEK, ERK, and EGFR." (PMID 29132432, 2017). "Our results suggest that paxillin mutants through their interactions with BCL-2 and DRP-1 could regulate cisplatin drug resistance in human lung cancer cells." (PMID 26980710, 2016). "Our data also reveal that the inhibitory effect of rhodomycin A on lung cancer progression may act through suppressing the Src-related multiple signalling pathways, including PI3K, JNK, Paxillin, and p130cas." (PMID 26312766, 2015). "Our data indicated that digoxin suppresses FAK-Src, paxillin, PI3K/AKT, MEK/ERK, STAT3 and p130Cas-JNK signaling pathways in various EGFR-containing lung cancer cells, suggesting that digoxin inhibits cancer cell invasion by decreasing Src activation and the activation of related signaling pathways." (PMID 25955608, 2015). "Moreover, in the same lung cancer samples from the tissue microarray, CD155 and PXN consistently exhibited similar expression patterns that both proteins were highly expressed in the high-expression group and markedly reduced in the low-expression group (middle and bottom)." (PMID 40634277, 2025). "Taken together, these results suggested that treatment with DBL may act as a potential candidate to inhibit lung cancer metastasis by inhibiting MMP-2 and -9 via affecting PI3K/AKT, MAPKs, FAK/paxillin, EMT/Snail and Slug, Nrf2/antioxidant enzymes, and NFκB signaling pathways." (PMID 28350337, 2017). "In addition, A5 Nb did not significantly alter Src/PXN/FAK activation or expression in CD155 low-expressing H460 and H520 lung cancer cell lines." (PMID 40634277, 2025).
gastric cancer (27 papers, 2009 to 2025). A primary or metastatic malignant neoplasm involving the stomach. "As PXN expression is associated with distant metastasis in gastric cancer patients, we then evaluated the potential role of PXN on cellular migration by transwell assays." (PMID 24180516, 2013). "Higher paxillin expression in adenoma and intestinal-type carcinoma indicated that paxillin overexpression may be closely linked to the intestinal carcinogenic pathway of gastric cancer." (PMID 24348846, 2014). "However, further study is needed to investigate the underlying mechanism involved in PXN regulation in gastric cancer." (PMID 24180516, 2013). "In addition, in a large cohort of gastric cancer patients, overexpression of PXN was significantly associated with aggressive tumor characteristics, such as distant metastasis and advanced TNM stage." (PMID 24180516, 2013). "Furthermore, IRS1 Gly972Arg variations may be associated with an increased susceptibility to develop gastric cancer 39.The important cellular adhesion factor Paxillin (PXN) is a hallmark protein in focal adhesion (FA) site." (PMID 33162799, 2020). "Silencing lncRNA XIST can also promote gastric cancer cell apoptosis through the lncRNA XIST/miR-132/paxillin signaling axis." (PMID 37175948, 2023). "Fibronectin promotes the phosphorylation of paxillin (tyr118) to promote gastric cancer cell invasion." (PMID 37175948, 2023). "The overexpression of paxillin promotes the proliferation of glioma cells, gastric cancer, cervical cancer, and colon cancer." (PMID 37175948, 2023). "Confocal imaging displayed that more and larger paxillin clusters were detected in RTN2-overexpressed gastric cancer cells." (PMID 35428758, 2022). "miR-216b overexpression enhances the activation of PI3K/AKT by partially regulating PXN in gastric cancer cells." (PMID 36467881, 2022). "LncRNA MALAT1 vias VE-cadherin/β-catenin complex, ERK/MMP, and FAK/paxillin signal transduction pathway to regulate the VM formation of gastric cancer cells." (PMID 33542193, 2021). "In gastric cancer, the lncRNA XIST, when overexpressed, adsorbed miR-132 and caused upregulation of PXN in cancer cells." (PMID 34946859, 2021). "Protein modulation through overexpression and inhibition approaches revealed that paxillin is a key regulator of proliferation and migration of gastric cancer cells." (PMID 32046329, 2020). "A similar tendency was observed for paxillin, which was aberrantly upregulated in gastric cancer tissues and cell lines." (PMID 32046329, 2020). "In fact, Chen and collaborators evaluated a large series of 239 gastric cancer patients and established a direct correlation between paxillin expression and distant metastasis, as well as advanced tumor stage." (PMID 32046329, 2020). "Functional experiments revealed that MALAT1 can regulate expression of classical VM markers, such as VE-cadherin, β-catenin, MMP-2/9, MT1-MMP, p-ERK, p-FAK and p-paxillin, and MALAT1, whose levels were also associated with OS in stage gastric cancer patients." (PMID 32169087, 2020). "Other secondary networks represented in gene expression profile of c.1380delA SB.mhdgc.-1 gastric cancer cells include cytoskeletal regulators like actin, paxillin, or β-catenin." (PMID 28460635, 2017). "Previously, we have found that L1cam plays a critical role in the progression of gastric cancer and Paxillin is a prognostic indicator of gastric cancer patients." (PMID 27620004, 2016). "Previously, we have found that L1cam plays an important role in the progression of gastric cancer and Paxillin is a prognostic indicator of gastric cancer patients." (PMID 25869101, 2015). "The present study aimed to investigate the clinicopathological and prognostic significance of paxillin in gastric cancer." (PMID 24348846, 2014). "Paxillin expression was compared with the clinicopathological and prognostic features of gastric cancer." (PMID 24348846, 2014).
gastric cancer (continued). "MELK promotes cell migration and invasion via the FAK/Paxillin pathway, and plays an important role in the occurrence and development of gastric cancer." (PMID 24885567, 2014). "In the present study, for the first time, we analyzed the correlation between paxillin expression and the survival rate of 392 patients with gastric carcinoma." (PMID 24348846, 2014). "In conclusion, our study revealed a cell adhesion protein PXN is frequently up-regulated in gastric cancer tissues and cell lines." (PMID 24180516, 2013). "Multivariate analysis demonstrated that PXN expression was an independent prognostic factor for gastric cancer patients." (PMID 24180516, 2013). "Kaplan-Meier analysis with log-rank test was employed to investigate the prognostic role of PXN for gastric cancer patients." (PMID 24180516, 2013). "Consistent with the level of protein, real-time PCR analysis confirmed PXN mRNA level was elevated in all five gastric cancer cell lines." (PMID 24180516, 2013). "Overexpression of PXN was correlated with distant metastasis (P = 0.001) and advanced tumor stage (P = 0.021) in gastric cancer patients." (PMID 24180516, 2013). "The expression of PXN was determined in paired gastric cancer tissues and adjacent normal tissues by Western blotting and real-time PCR." (PMID 24180516, 2013). "Multivariate analysis indicated only distant metastasis and PXN expression were independent prognostic factors for gastric cancer patients (P < 0.001 and P = 0.020, respectively)." (PMID 24180516, 2013). "PXN was up-regulated in gastric cancer tissues and cell lines as compared with adjacent normal tissues and normal gastric epithelial cell line GES-1." (PMID 24180516, 2013). "In this study, we found that ectopic expression of PXN stimulated tumor proliferation and migration whereas knockdown of PXN suppressed cellular growth and motility in gastric cancer cells." (PMID 24180516, 2013). "Taken together, these results suggest that PXN plays an important role in the growth and metastasis of gastric cancer." (PMID 24180516, 2013). "We further investigated the expression of PXN in 239 paraffin-embedded gastric cancer tissues by IHC." (PMID 24180516, 2013). "Thus, the antagonist prevented the stabilization of integrin αβ1 clustering in gastric cancer cells, inhibiting phosphorylation of focal adhesion kinases (FAK) and its adaptor protein, paxillin, decreasing the invasion of gastric cancer cells." (PMID 38562556, 2024). "Similarly, paxillin has been shown to be highly expressed in gastric cancer tissues and cell lines; patients with a high paxillin expression not only have a poor prognosis, but this high expression also promotes proliferation and migration in vitro." (PMID 37175948, 2023). "Interestingly overexpression of TXNDC12 significantly enhanced FAK phosphorylation at Tyr-397 and paxillin phosphorylation at Tyr118, suggesting the role of TXNDC12 in the FAK/paxillin pathway in gastric cancer." (PMID 35965326, 2022). "Steroid hormones may affect cancer cell migration; for example, 17β-estradiol suppresses IL-6-dependent tyrosine phosphorylation of Src, p130Cas, and paxillin in gastric cancer cells." (PMID 27698389, 2016). "However, paxillin expression was negatively correlated with tumor size, depth of invasion and lymph node metastasis of gastric cancer in the present study." (PMID 24348846, 2014). "When stratified according to the depth of invasion, the significant correlation disappeared in the early gastric cancers, but not in the advanced ones, indicating that the association between paxillin expression and prognosis depends on the depth of invasion." (PMID 24348846, 2014). "Altered paxillin expression may, therefore, be employed as an indicator of pathobiological behaviors and prognosis of gastric carcinomas." (PMID 24348846, 2014). "Aberrant paxillin expression may be involved in the growth, invasion, metastasis and differentiation of gastric carcinoma." (PMID 24348846, 2014).
gastric cancer (continued). "Ectopic expression/knockdown of PXN promotes/inhibits tumor growth and migration, which indicates that PXN may play an important role in the progression and metastasis of gastric cancer." (PMID 24180516, 2013). "Moreover, Western blot analysis showed the expression levels of PXN were higher in gastric cancer cell lines than that of normal gastric epithelial cell line GES-1." (PMID 24180516, 2013). "In this study, firstly, we detected the expression of PXN in gastric cancer tissues and cell lines." (PMID 24180516, 2013). "Immunohistochemistry was performed to detect the expression of PXN in 239 gastric cancer patients." (PMID 24180516, 2013). "The protein and mRNA level of PXN was evaluated in gastric cancer tissues and cell lines." (PMID 24180516, 2013). "Additionally, the effects of PXN on gastric cancer cell proliferation and migration were also evaluated." (PMID 24180516, 2013). "PXN plays an important role in tumor progression and may be used as a potential prognostic indicator in gastric cancer." (PMID 24180516, 2013). "Furthermore, MELK was found to promote cell migration and invasion via the FAK/Paxillin pathway, which could thus be a potential focus of future therapy against gastric cancer." (PMID 24885567, 2014). "Furthermore, ectopic expression/knockdown of PXN could promote/inhibit cell proliferation and migration in gastric cancer cells." (PMID 24180516, 2013). "However, further studies are needed to confirm the clinical role of PXN in gastric cancer." (PMID 24180516, 2013). "However, the clinicopathological and prognostic role of PXN in gastric cancer is still unclear." (PMID 24180516, 2013). "17β-estradiol has also been reported to inhibit the migration of gastric cancer cells by inhibiting CCL-5 and the IL-6-induced phosphorylation of Src, Cas, and paxillin in human gastric cancer cells." (PMID 37175948, 2023). "The long non-coding RNA MALAT1 can promote gastric cancer VM and angiogenesis through the ERK/MMP and FAK/paxillin signaling pathways." (PMID 37175948, 2023). "Here, we further identified the role of Src in IL‐8‐up‐regulated phosphorylation/activation of Cas, paxillin, ERK1/2 and JNK1/2 in human gastric cancer cells." (PMID 26945908, 2016). "However, the potential clinical and pathologic role of PXN in gastric cancer is still unknown." (PMID 24180516, 2013). "Our results demonstrate significantly greater expression of fascin-1, ezrin and paxillin in LSCC than ANM tissues, which agrees with observations in ESCC, gastric cancer, and NSCLC." (PMID 23209815, 2012). "However, IL‐8‐up‐regulated activation of Src (Tyr416), Cas (Tyr165), paxillin (Tyr118), ERK1/2 (Thr202, Tyr204) and JNK1/2 (Thr183,Tyr185) were significantly inhibited by 17β‐estradiol (E2; 10−8 and 10−9 M) treatment in human gastric cancer cells." (PMID 26945908, 2016). "In the present study, we observed that 17β‐estradiol treatment significantly inhibited HBMMSCS‐mediated cell motility activity through suppressing IL‐8‐Src downstream target protein activation and expression, including Cas, paxillin, ERK1/2, JNK1/2, MMP9, tPA and uPA in human gastric cancer cells." (PMID 26945908, 2016). "Furthermore, ERp19 knockdown dramatically suppressed gastric cancer cell growth, inhibited cellular migration/invasion and down-regulated the phosphorylation of FAK and paxillin, whereas ERp19 over-expression reversed these changes." (PMID 25940440, 2015). "In paired primary gastric cancer tissues and adjacent nontumorous tissues, Western blot analysis revealed overexpression of PXN in cancer tissues compared with adjacent nontumorous tissues." (PMID 24180516, 2013). "The results showed that PXN was frequently up-regulated in gastric cancer tissues and cell lines compared with adjacent nontumorous tissues or normal gastric mucosa cells." (PMID 24180516, 2013).
gastric cancer (continued). "The multivariate analysis demonstrated that patient age, depth of invasion, lymphatic invasion, lymph node metastasis, TNM staging and Lauren classification, but not patient gender, tumor size, venous invasion or paxillin expression, were independent prognostic factors for all gastric carcinomas." (PMID 24348846, 2014).